IL5 (interleukin 5)
Diseases named in the same sentence as IL5 in open-access papers (continued):
Sharing a sentence is not in itself a finding about the gene and the disease.
bladder cancer (7 papers, 2012 to 2025). "This study suggests the presence of specific inflammatory cytokine (IL-5, IL-20, and IL-28A)-mediated association in bladder cancer development." (PMID 22962576, 2012). "The presence of eosinophils in different amounts within the stroma of 66 bladder cancers (42.3%) is obviously due to the action of potent eosinophil chemoattractants, such as eotaxin, platelet activating factor, C5a, interleukin-5, and immunoglobulin E (IgE)." (PMID 30443450, 2018). "Our data showed that IL-5, IL-20, and IL-28A stimulated the migration and invasion of bladder cancer cells." (PMID 22962576, 2012). "Because signaling for cytokines primarily activates the Jak/Stat and MAPK signal transduction pathways, we next investigated the signaling cascades induced by IL-5, IL-20, and IL-28A in bladder cancer cells." (PMID 22962576, 2012). "The present results indicate that transcription factors NF-κB and AP-1 are the main factors for MMP-9 induction in response to IL-5, IL-20, and IL-28A in bladder cancer cells." (PMID 22962576, 2012). "In the present study, both IL-5 and IL-5Rα were detected by RT-PCR and immunoblot in bladder cancer cells." (PMID 22962576, 2012). "Our observation in this experiment is consistent with a recent report showing that the circulatory levels of IL-4, IL-5, and IL-10 were significantly higher in bladder cancer patient serum than in normal samples." (PMID 22962576, 2012). "To this end, we performed an electrophoretic mobility shift assay (EMSA) using nuclear extracts of bladder cancer cells induced by IL-5, IL-20, and IL-28A." (PMID 22962576, 2012). "Among the 10 up-regulated molecules examined, the capacity for both wound-healing migration and invasion was enhanced in response to IL-5, IL-20, and IL-28A in bladder cancer cell lines (253J and EJ cells), compared with untreated cells." (PMID 22962576, 2012). "Also in bladder cancer, elevated IL-5 levels enhance bladder cancer cell migration and invasion through the extracellular signal-regulated kinase 1/2-mediated matrix metallopeptidase 9/nuclear factor κ/activator 1 pathway." (PMID 36531035, 2022). "Among the genes and proteins examined, we observed that IL-5, IL-20, IL-28A, and their receptors produced by bladder cancer cells induced migration, invasion, transcription factor-mediated MMP-9 expression, and activation of signaling pathways, such as the MAPK and Jak-Stat pathways." (PMID 22962576, 2012). "Finally, activation of MAPK and Jak-Stat signaling was observed after the addition of IL-5, IL-20, and IL-28A to bladder cancer cells." (PMID 22962576, 2012). "In addition, we also identified that MAPK and Jak/Stat signaling are activated in bladder cancer cells following treatment with IL-5, IL-20, and IL-28A." (PMID 22962576, 2012). "IL-5, IL-20, and IL-28A may thus be major molecules that characterize the migration and invasiveness of TCC, as well as the development of bladder cancer associated with disease progression." (PMID 22962576, 2012). "Thus, our results are the first to suggest that IL-5, IL-20, and IL-28A act as novel factors of migration and invasion in bladder carcinoma cells." (PMID 22962576, 2012). "The use of rBCG vaccines for the treatment of bladder carcinomas did not produce TH-2 type cytokines including IL-5 levels." (PMID 22962576, 2012). "Unexpectedly, the results of the present study showed that 3 kinds of cytokines (IL-5, IL-20, and IL-28A) correlate with metastatic potential without altering cell proliferation, which results in bladder cancer cell migration and invasion through MMP-2 and MMP-9 expression." (PMID 22962576, 2012). "However, AKT activation was not influenced in IL-5-, IL-20-, and IL-28A-treated bladder cancer cells." (PMID 22962576, 2012).
bronchiolitis (7 papers, 2014 to 2025). Inflammation of the bronchioles characterized by swelling of the bronchioles and mucus accumulation. "For example, IL-5 (−746) SNP has been associated with worse lung functions in asthmatic children and IL-8 (−251) SNP with an increased risk for bronchiolitis with respiratory syncytial virus infection." (PMID 24718616, 2014). "Along these lines, acute bronchiolitis caused by RSV infection is known to activate Th2 cell–related cytokines such as IL–4 and IL–5, resulting in an imbalanced immune response leading to airway mucus overproduction." (PMID 35603159, 2022). "The bronchiolitis group serum IL-5, IL-9, IL-13, IL-33, TSLP protein levels were higher than the normal control group." (PMID 33514798, 2021). "We used ELISA to detect IL-4, IL-5, TNF-α, and IgE in the serum of children in both groups, and the results suggested that IL-4, IL-5, TNF-α, and IgE were significantly elevated in children with bronchiolitis compared with healthy children." (PMID 37389334, 2023).
childhood asthma (7 papers, 2011 to 2025). "Another multicentre prospective study reported that higher nasopharyngeal airway type 2 cytokine (IL-4, IL-5, IL-13, and TSLP) levels in infants with HRV infection alone were associated with a greater risk of developing childhood asthma." (PMID 40852413, 2025). "Our GWAS dataset supported an association between identical SNPs reported in ORMDL3/GSDMB/GSDMA, IL5/RAD50/IL13, HLA-DR/DQ, and SMAD3 and pediatric asthma (P<0.05)." (PMID 21814517, 2011).
gastric cancer (7 papers, 2002 to 2025). A primary or metastatic malignant neoplasm involving the stomach. "Gastric carcinomas have been shown to express eosinophil chemotactic cytokines including IL-2, IL-5 and GM–CSF and expression of GM–CSF appears to be specific for signet ring carcinoma cells." (PMID 11875724, 2002). "Our data showed that the mRNA expression levels of the transcription factors RORα and GATA3, the receptors T1/ST2 and IL-17RB, surface markers CRTH2, and type 2 cytokines IL-33, IL-5, and IL-4 were significantly increased in PBMCs from patients with gastric cancer compared to healthy controls." (PMID 24741632, 2014). "We aimed to evaluate the IL-5 and IFN-γ level with the response of anti-PD-1 blockade in non-small-cell lung cancer (NSCLC) and gastric cancer (GC)." (PMID 34239620, 2021). "To understand the relationship of RORα and ILC2s-related markers and signature cytokines in patients with gastric cancer, we analyzed the correlation between RORα and T1/ST2, IL-17RB, CRTH2, ICOS, CD45, IL-13, and IL-5 in mRNA levels." (PMID 24741632, 2014). "For downstream inflammatory factors, our findings were supported by previous studies that demonstrated a strong association between pre-neoplastic alterations and the development of gastric cancer, involving various inflammatory regulators including bNGF, GCSF, IL-13, IL-5, IL-7, and MCSF." (PMID 39439893, 2024).
ischemic stroke (7 papers, 2016 to 2024). A stroke disorder caused by obstruction of blood flow to the brain, due to thrombotic (local blood clot formation) or embolic (due to a blood clot or other material traveling from another site) event. "Li's study showed that the serum IL-4, IL-5, IL-7, and IL-9 levels decreased in the ischemic stroke patients with poor outcome." (PMID 36875689, 2023). "Studies have found that the expression levels of IL-4, IL-5, IL-6, and IL-10 are increased remarkably in the damaged hemisphere after ischemic stroke." (PMID 31164999, 2019). "Genetic studies have identified single nucleotide polymorphisms (SNPs) that are associated with increased risk of CAD in the interleukin-5 gene (IL5) and increased risk of ischemic stroke in the interleukin-5 receptor alpha subunit gene (IL5RA)." (PMID 26821299, 2016). "Genetic variants in the IL5 locus have been associated with increased risk of CAD and ischemic stroke." (PMID 26821299, 2016).
myeloma (7 papers, 2013 to 2023). "At baseline, most Th2 cytokines (i.e., IL-4, IL-5, IL-6, and IL-13) were elevated in the multiple myeloma patients, compared to healthy controls, and most patients had a Th1/Th2 score <1.0, suggesting Th2 dominance." (PMID 34239993, 2021). "Consistent with the effect of anti-IL-5 blocking antibodies on the myeloma load after injection of high numbers of MOPC315.BM cells, eosinophil-depletion showed its capacity to reduce early myeloma growths." (PMID 25272036, 2014). "Together, these data indicate that depletion of eosinophils - either by anti-IL-5 or in genetically modified mice - impairs the growth of MOPC315.BM myeloma cells in the bone marrow during early myeloma development." (PMID 25272036, 2014). "Two weeks after MOPC315.BM injection, the myeloma load was approximately 30% reduced in anti-IL-5 treated mice, as measured by myeloma-specific anti-DNP protein in serum." (PMID 25272036, 2014). "Impact of anti-IL-5 treatment on incidence of early myeloma development." (PMID 25272036, 2014). "Hence, excluding the possibility that the decrease of myeloma specific protein in anti-IL-5 treated mice was due to suppression of antibody secretion." (PMID 25272036, 2014). "Depletion of eosinophils in vivo by IL-5 blockade led to a reduction of the early myeloma load." (PMID 25272036, 2014). "Therefore, we conclude that treatment of early stage multiple myeloma with anti-IL-5 blocking reagents is worth a trial in patients." (PMID 25272036, 2014). "Of note, IL-5 has not been implicated as a growth factor for myeloma cells and does not support the growth of MOPC315.BM cells in vitro." (PMID 25272036, 2014). "Notably, IL-5 blockade-mediated eosinophil depletion reduced the early myeloma load, providing a proof of principle that therapeutic targeting of hematopoietic components of plasma cell niches represents a novel strategy for suppressing multiple myeloma." (PMID 25272036, 2014). "Four weeks after injection, myeloma specific anti-DNP was present in all mice of the control group (10/10), but in only 70% (7/10) of IL-5 treated mice." (PMID 25272036, 2014). "In addition, IL-3 and IL-5 share a common signal transduction chain, KH97, with CSF2, which can increase the sensitivity of myeloma cells to these cytokines." (PMID 37250588, 2023). "As the role of IL-5 as growth factor for myeloma plasma cells is debated, and IL-5 should not impact on BM stromal cells, one mechanism by which anti-IL17, anti-IL-17RA, and anti-IL5 antibodies acted in Vk*MYC mice is a reduced accrual and survival of eosinophils and consequently of Th17 cells." (PMID 30510245, 2018). "Of note, IL-5 did not support the secretion of myeloma specific anti-DNP antibodies." (PMID 25272036, 2014).
non-small cell lung carcinoma (7 papers, 2013 to 2025). A group of at least three distinct histological types of lung cancer, including non-small cell squamous cell carcinoma, adenocarcinoma, and large cell carcinoma. "Additionally, preoperative blood samples from non-small cell lung cancer (NSCLC) patients exhibited significantly elevated IL-5 levels, which markedly decreased following tumor resection." (PMID 40136462, 2025). "Non-small cell lung cancer (NSCLC) biopsy specimens have high intratumoral concentrations of CXCR2 ligands (CXCL1, CXCL5, and CXCL8) and type 2 cytokines interleukin-4 (IL-4), IL-5, IL-10, and IL-13." (PMID 23665907, 2013).
pancreatic cancer (7 papers, 2012 to 2025). "Studies have indicated that eosinophils and pancreatic cancer may be associated with inflammatory response, IL-5, IL-18, and degranulation, even if the precise mechanism behind this association is still unclear." (PMID 39465831, 2024). "In pancreatic cancer progression, IL-5/IL-5Rα roles are possibly a double-edged sword, with both pro- and antitumor activities recently discovered." (PMID 38474359, 2024). "Research has demonstrated that the pathological characteristic of pancreatic cancer is pancreatic fibrosis, and that IL-5 contributes to the development of pancreatic fibrosis." (PMID 39465831, 2024). "Results suggest that pancreas localized IL-5 stimulates the increase of IL-5Rα on ductal tumor cells and increases pancreatic tumor motility." (PMID 32552827, 2020). "Collectively, IL-5/IL-5Rα signaling in the pancreatic tumor microenvironment is a novel mechanism to facilitate tumor progression." (PMID 32552827, 2020). "Collectively, IL-5/IL-5Rα signaling in the mouse and human pancreatic tumors microenvironment is a novel mechanism to facilitate tumor progression." (PMID 32552827, 2020). "Results suggest that IL-5 in the pancreatic compartment stimulates increased IL-5Rα on ductal tumor cells to increase pancreatic tumor motility." (PMID 32552827, 2020). "However, the effect of ER-stressed inhibitors, including TM, on IL-5 in pancreatic cancer cells and localized eosinophils is still uncertain." (PMID 38474359, 2024). "Findings led to the discovery of a new signaling mechanism of crosstalk between IL-5 expression in the pancreatic microenvironment and IL-5Rα on pancreatic tumor cells, which may be a novel targetable pathway in pancreatic tumor progression." (PMID 32552827, 2020). "Eosinophil-supporting cytokine interleukin-5 and receptor are likely to have a role, but the significance in the pancreatic cancer microenvironment is unknown." (PMID 32552827, 2020). "A therapy based on Th2 cells or IL-5 may be a valuable alternative for patients with gastrointestinal cancers and should be considered as a new treatment option for patients with colon and pancreas cancers." (PMID 36376448, 2023). "Further, studies have shown that ER-stressed inhibitors reduce IL-5 production in Th-2 cells (naïve CD4+ T cells), which inhibit colon and pancreatic cancer growth by promoting antitumorigenic responses from macrophages and eosinophils." (PMID 38474359, 2024). "IL-5 stimulated tumor cell migration and activation through STAT5 signaling, thereby suggesting an unreported tumor-promoting role for IL-5Rα in pancreatic cancer." (PMID 32552827, 2020). "In the case of advanced lesions, pro‐inflammatory cytokines like L‐1beta, IL‐5, IL‐6, IL‐8 and TNF‐alpha were elevated in high‐grade dysplasia/pancreatic cancer compared to low‐grade/moderate dysplasia group, suggesting that immune response patterns may change across the natural history of disease." (PMID 39482824, 2025). "Finally, using multiplex analysis, we find that IL-5, but not IL-4 or IL-13 is hypersecreted from colon and pancreas tumors obtained from mice treated with Th2 cells." (PMID 36376448, 2023). "However, despite confirming that PPIA induced a relatively high increase in IL-5 in PANC-1 cells, there was no similar response detected in any of the other cell lines that included the other pancreatic cancer cell line, L3.6pL." (PMID 22631225, 2012).
bronchitis (6 papers, 2012 to 2025). An acute or chronic inflammatory process affecting the bronchi. "There is significant deference between the values of IL-5 in asthmatics versus group of patients with bronchitis and healthy controls." (PMID 27275299, 2015). "Hence, controlling for respiratory infections or excluding children with wheezy bronchitis did not essentially affect the associations of IL-5, IL-13, CXCL10, IgA, and TGF-β1 in both serum and whey with AS." (PMID 22805009, 2012).
cervical cancer (6 papers, 2015 to 2024). A primary or metastatic malignant neoplasm involving the cervix. "An increased survival rate in patients with cervical cancer was associated with IL-5 < 1.70 pg/mL, IL-17 < 2.30 pg/mL, and IFN-α < 2.26 pg/mL preoperatively." (PMID 36053326, 2023). "At diagnosis, our findings showed that plasma levels of sHLA-G and IL-5, IL-6, IL-8, IL-10, IL-17, and were significantly increased in patients with cervical cancer." (PMID 36053326, 2023). "Tumor-derived thymic stromal lymphopoietin (TSLP) can activate eosinophil to increase the expression of IL-4, IL-5, IL-10 and IL-13, and promote the proliferation of cervical cancer cells." (PMID 36874093, 2023). "Although a Th2 response is regarded as immunosuppressive in cervical cancer, HPV-specific T cells associated with regression of high-grade VIN lesions, have been shown to produce high levels of both IFNy and IL-5." (PMID 25889974, 2015). "Since the immune response in cervical cancer is predominantly characterized by Th1, Th2, Th17 and Treg cells, the contributions of the ‘T cells’ signature marker TBX21 and the ‘Th2’ signature marker IL5 were studied." (PMID 25889974, 2015). "Measuring IL6, IL5 and IL17 expression may improve the accuracy of predicting prognosis in cervical cancer." (PMID 25889974, 2015).
cognitive decline (6 papers, 2016 to 2025). "The authors concluded that microglial activation is a major causal factor, as its removal prevented cognitive decline and reduced a broad spectrum of cytokines (IL-1α, IL-1β, IL-3, IL-4, IL-5, GM-CSF)." (PMID 41155372, 2025). "On the other hand, IL-5 presents functions associated with reduced aging-associated neuroinflammatory processes and improvement of cognitive decline observed in older adults." (PMID 36211483, 2022). "In the aMCI group, higher baseline plasma levels of IL-2, sCD40L, and VEGF were associated with a lower cognitive decline, and in the AD group, higher baseline plasma levels of IFNγ, IL-5, IL-17A, IL-25, FGF, GM-CSF, and VEGF were associated with a more rapid cognitive decline." (PMID 34122046, 2021). "Higher baseline levels of IL-2, sCD40L, IL-8, and VEGF were associated with a lower annual cognitive decline in the aMCI group, and higher baseline levels of Aβ1–40, IFNγ, IL-5, IL-17A, IL-25, and FGF were associated with a rapid annual cognitive decline in the AD group." (PMID 34122046, 2021). "Furthermore, IL-2, IL-17, IL-23, TNF-β, GM-CSF, MCP-1, RANTES, eotaxin, IL-4, IL-5, IL-10 and G-CSF are also closely related with cognitive decline with ageing, synaptic or neuronal loss, osteoarthritis cancer, lung senescence." (PMID 27105505, 2016). "In contrast, the AD group showed that the higher baseline levels of IFNγ (r = −0.701, p = 0.036), IL-5 (r = −0.756, p = 0.019), IL-17A (r = −0.759, p = 0.021), IL-25 (r = −0.840, p = 0.036), and FGF (r = −0.780, p = 0.013) were significantly correlated with more rapid cognitive decline." (PMID 34122046, 2021).
cryptococcal infection (6 papers, 2015 to 2020). "While type-1 immune responses have been shown to drive protective immunity against cryptococcal infection, type 2-skewed immune responses defined by the production of IL-4, IL-5, and IL-13 play deleterious roles in infection with C. neoformans." (PMID 30520685, 2019). "Pulmonary cryptococcal infection resulted in a progressive accumulation of Cda2-MHCII-specific T cells in the lungs that predominately expressed the Th2 cytokines IL-5 and/or IL-13." (PMID 25764512, 2015). "We further examined the effect of IFNAR1 deficiency on the Th2 response by measuring the production of IL-4, IL-5, and IL-13 in the lungs on day 3, 7, 14, and 28 after cryptococcal infection." (PMID 26384031, 2015). "It has also been previously reported that IL-5-/- and eosinophil-deficient PHIL mice have little to no change in infectious outcomes during cryptococcosis, although the data was not formally shown." (PMID 30897162, 2019).